HIF1A (hypoxia inducible factor 1 subunit alpha)
Diseases named in the same sentence as HIF1A in open-access papers (continued):
Sharing a sentence is not in itself a finding about the gene and the disease.
breast cancer (continued). "High concentrations of HIF1α in renal and breast cancer cell lines were shown to increase cancer cell survival, whereas in ovarian cancer high HIF concentrations contributed to increased apoptosis." (PMID 23342109, 2013). "Insulin also induces leptin expression in breast cancer cells by increasing HIF-1α and SP1 binding to the leptin promoter." (PMID 24202338, 2013). "Hypoxia inducible factor-1α (HIF-1α), a key mediator of cellular adaptation to low oxygen levels, is emerging as a novel prognostic marker in breast cancer." (PMID 23566437, 2013). "Taken together, these results suggest a functional link between HIF-1α and the hypoxic response in breast cancer cells." (PMID 24860738, 2013). "Double immunohistochemistry for HIF-1α and aromatase was performed on tissues obtained from breast cancer and cancer-free patients." (PMID 23566437, 2013). "Accumulating evidence indicates that HIF-1α is significantly correlated with the rate of CSCs that express CD44+CD24−/low in the early stage of breast cancer." (PMID 23314174, 2013). "ERK1/2 activated by hypoxia induces HIF-1α expression through the generation of reactive oxygen species and activates Rac1 in breast cancer cells." (PMID 24349381, 2013). "It was previously shown that HIF-1α promote formation of osteolytic bone metastases from breast cancer cell, MDA-MB-231, and that was through stimulating angiogenesis, osteoclastogenesis and inhibition of differentiation of osteoblasts." (PMID 24558636, 2013). "We first determined that hypoxia induces the expression of HIF-1α and GPER in CAFs, then we ascertained that the HIF-1α/GPER signaling is involved in the regulation of VEGF expression in breast cancer cells and in CAFs exposed to hypoxia." (PMID 23947803, 2013). "miR-519c reduced HIF-1α levels, suppressing tumor formation and angiogenesis in lung and breast cancer cell lines, while it also inhibited the biosynthesis of HuR, which regulates numerous cancer traits, including angiogenesis." (PMID 23325049, 2013). "In breast cancer cells, hypoxia has been shown to promote the release of exosomes, which is partly mediated by HIF-1α." (PMID 24860738, 2013). "Results demonstrated that there is a significant increase in the percentage of HIF-1α positive ASCs in breast cancer patients compared to cancer-free women." (PMID 23566437, 2013). "It seems that in the context of breast cancer, the most important is contribution of prolidase to regulation of HIF-1α." (PMID 23549681, 2013). "In this study we have found that prolidase activity reflects nuclear localization of HIF-1α in breast cancer cells." (PMID 23549681, 2013). "Using the same bone metastasis model of intracardiac inoculation of MDA-MB-231 breast cancer cells, we tested the effects of a combined treatment of SD-208 and 2-methoxyestradiol, an inhibitor of HIF-1α, the key mediator of hypoxia." (PMID 24558636, 2013). "VEGF promoter deletion and siRNA analyses showed that leptin signaling regulates VEGF in breast cancer mainly through HIF-1α and NFκB in normoxic conditions." (PMID 24202338, 2013). "Oxygen radicals and hypoxia co-operatively promote tumor angiogenesis, in which VEGF overexpression is stimulated by the activation of HIF-1α and NFκB pathways in breast cancer." (PMID 23638734, 2013). "When the breast cancer cells were co-cultured with TAMs, they expressed increased levels of HIF-1α and NF-κB." (PMID 25068070, 2013). "YC-1 also reduced basal levels of VEGF secretion from T47-D breast cancer cells, most likely by inhibiting HIF-1α, which is the major transcription factor required for VEGF induction, though this remains to be proven." (PMID 23123638, 2013). "The role of estrogen in breast cancer progression and activation of prolidase activity and HIF-1α led us to study the effect of estrogen on nuclear HIF-1α expression in breast cancer estrogen-dependent MCF-7 and estrogen-independent MDA-MB-231 cells." (PMID 23549681, 2013).
breast cancer (continued). "Taken together, our findings indicate that hypoxia induces NMB-R expression through a novel mechanism to regulate HIF-1α expression in breast cancer cells." (PMID 24349381, 2013). "The current study was therefore undertaken to characterize the effect of estrogen on HIF-1α expression in breast cancer estrogen-dependent MCF-7 and estrogen-independent MDA-MB-231 cell lines." (PMID 23549681, 2013). "Only 24 (3.3%) and 4 (0.6%) of 721 breast cancers displayed HIF-1α expression in the nucleus and cytoplasm, respectively." (PMID 23888270, 2013). "Previous studies have demonstrated that HIF-1α is a novel prognostic marker in determining the aggressive phenotype of breast cancer and is emerging as a potential target for cancer treatment." (PMID 23566437, 2013). "Another study has shown that HIF-1α mRNA and protein expression levels are increased in human breast cancer tissue." (PMID 23737911, 2013). "DDX3 was overexpressed in 127 of 366 breast cancer patients, and was correlated with overexpression of HIF-1α and its downstream genes CAIX and GLUT1." (PMID 23696831, 2013). "In this study, novel evidence is provided for the regulation of HIF-1α and its role in regulating aromatase expression in adipose stromal cells in the context of obesity and breast cancer." (PMID 23566437, 2013). "Epo, a downstream protein of HIF-1α, has been observed to counteract the hypoxia-induced apoptosis of breast cancer cells." (PMID 23833638, 2013). "We indeed show a positive correlation between HIF-1α and DDX3 overexpression in a large series of human breast cancer cases, as well as an association between DDX3 overexpression and various other hypoxia related proteins." (PMID 23696831, 2013). "In the present study, we found that exposure to hypoxic conditions increases the levels of NMBR mRNA and protein in breast cancer cells, which are tightly regulated by hypoxia-inducible factor-1α (HIF-1α)." (PMID 24349381, 2013). "CXCR4 expression is increased by HIF-1α, and a study revealed higher expression of HIF-1α in breast carcinomas of patients with bone marrow metastasis." (PMID 24376734, 2013). "Other lysyl oxidase-like enzymes that are regulated by HIF-1α also play an important role in the formation of breast cancer metastatic niche." (PMID 23241400, 2012). "HIF-1α rather than HIF-2α is the predominant regulator of the hypoxic response in breast cancer; therefore, we sought to determine the effect of Hif1a deletion in the MMTV-PyMT model of breast cancer." (PMID 22225988, 2012). "The data collectively identified, for the first time, HIF-1α as a regulator of CD44 expression in breast cancer cells and tumors." (PMID 22937154, 2012). "Here we have established the role of HIF-1α in regulating CD44 in MDA-MB-231 and SUM-149 breast cancer cells, and two of its variant isoforms in MDA-MB-231 breast cancer cells." (PMID 22937154, 2012). "In conclusion, previous studies have shown that HIF-1α pathway played important roles in the tumor growth and metastasis including major types of human tumors such as lung cancer, gastric cancer, breast cancer, prostate cancer, pancreatic cancer etc." (PMID 23300882, 2012). "Although the expression of the Jagged ligands has been reported to be hypoxia-inducible in breast cancer cell lines, we were unable to confirm a consistent effect of HIF-1α on the expression of either Jagged1 or Jagged2 by tumorspheres." (PMID 22225988, 2012). "Overexpression of the oxygen-responsive transcription factor hypoxia-inducible factor 1α (HIF-1α) correlates with poor prognosis in breast cancer patients." (PMID 22225988, 2012). "The oxygen-responsive hypoxia-inducible factor 1α (HIF-1α) protein, a master regulator of the hypoxic response, is overexpressed in a variety of carcinomas and their metastases, including breast cancer." (PMID 22225988, 2012).
breast cancer (continued). "Elevated expression of HIF-1α and the loss of prolyl hydroxylase enzyme 3 (PHD3) and factor inhibiting HIF (FIH) in the nucleus have been observed in 125 BRCA-associated breast cancers." (PMID 22007214, 2012). "The VEGF profile also correlates with the expression profile of three individual genes (Snail, Twist, and HIF-1α) and the intrinsic subtype of breast cancer." (PMID 22007214, 2012). "Overall, these results indicate that EGF is a potent regulator of HIF-1α expression in normoxic PyMT mammary tumor cells, as previously observed in SK-BR-3 and MCF-7 cells, and that EGF prolongs HIF-1α stabilization under hypoxic conditions." (PMID 22225988, 2012). "Herein we show for the first time that HIF-1α positively regulates TIC activity in breast cancer as suggested by sphere formation assays in vitro and validated through limiting dilution transplantation of WT and KO cells." (PMID 22225988, 2012). "Using these novel HIF-1α wild-type (WT) and HIF-1α-null (KO) mammary tumor epithelial cells (MTECs), we demonstrate that HIF-1α prominently augments primary tumor growth and lung metastasis and accelerates relapse due to metastasis." (PMID 22225988, 2012). "We have now created an improved model system in which Hif1a is efficiently deleted in the mammary tumor epithelium via ex vivo viral transduction with Cre recombinase prior to the injection of mammary tumor cells to the cleared fat pads of recipient mice." (PMID 22225988, 2012). "HIF-1α overexpression is more frequent in BRCA1-related breast cancer compared to that in sporadic cancer in a small series of 30 cases." (PMID 22007214, 2012). "Our data identified HIF-1α as a regulator of CD44 that increased the number of CD44 molecules and the percentage of CD44 positive cells expressing variant exons v6 and v7/8 in breast cancer cells under hypoxic conditions." (PMID 22937154, 2012). "Either the overexpression of HIF-1α protein or the enrichment of a hypoxic gene signature in the primary tumor correlates with poor prognosis and decreased survival in breast cancer patients." (PMID 22225988, 2012). "Our studies demonstrate that the hypoxic response, specifically through HIF-1α, is important for controlling breast cancer stem cell behavior through the regulation of CD133 and the Notch pathway." (PMID 22225988, 2012). "The module M10 was characterized by gene sets associated with angiogenesis in response to hypoxia (or HIF1A degregulation) and was a strong predictor of recurrence in Luminal and ERRB2 amplied breast cancer." (PMID 22789589, 2012). "PHD3 and FIH are responsible for the HIF-1α degradation and modulation observed in BRCA1-mutated breast cancers." (PMID 22007214, 2012). "Taken together, our results strongly suggest that increased HIF-1α protein accumulation in breast cancer lines by oestrogen is largely dependent upon HIF-1α translation." (PMID 21897387, 2011). "The regulation of HIF-1α by E2 can explain, in part, the role of oestrogen signalling in breast cancer progression." (PMID 21897387, 2011). "In summary, this study highlighted the role of Rac1 in the regulation of HIF-1α expression in hypoxic MCF-7 human breast cancer cells." (PMID 21980400, 2011). "In this study, we demonstrate that exposure of human breast cancer lines to 17β-oestradiol (E2) rapidly induced the expression of HIF-1α, the regulated subunit of HIF1, in normoxic condition." (PMID 21897387, 2011). "HIF-1α and its downstream genes such as VEGF and CAIX are associated with advanced tumour stage, metastases and a shorter survival in breast cancer." (PMID 21291529, 2011). "Elevated HIF-1α level is associated with the development of multiple neoplasms in Von Hippel–Lindu (VHL) disease and poor patient survival in breast cancer, signifying a decisive role in cancer development." (PMID 21897387, 2011). "In breast cancer cells, HIF-1α is normally expressed at low levels in normal culture conditions and elevated during hypoxic milieu." (PMID 21897387, 2011).
breast cancer (continued). "Our data have defined c-Src as a critical upstream activator in the oestrogen-stimulated HIF-1α expression in breast cancer lines." (PMID 21897387, 2011). "To conclude, ERα/c-Src/PI3K/Akt/mTOR signals elevate the levels of HIF-1α in response to oestrogen in ERα+ breast cancer lines." (PMID 21897387, 2011). "Others have shown that miR-20b limits HIF-1α expression in lung adenocarcinoma and breast cancer cell lines." (PMID 21629773, 2011). "The importance of HIF-1α as an oestrogen-inducible protein is of interest as it will enable us to understand further the oestrogen-induced cell proliferation and invasion in breast cancer." (PMID 21897387, 2011). "In the present study, HIF-1α mRNA and protein expression was increased breast cancer cells undergoing hypoxia." (PMID 21980400, 2011). "In another study by Lofsted and coworkers it was demonstrated that hypoxia upregulates Mxi-1 mRNA and protein in neuroblastoma and breast cancer cells, and Mxi-1 was confirmed as a direct HIF-1α target gene." (PMID 21925595, 2011). "In fact, others have reported increased HIF-1α expression when sub-confluent breast carcinoma cells were incubated with conditioned media from confluent cultures." (PMID 21284881, 2011). "Previous breast cancer studies showed that in hypoxic conditions, HIF-1α expression is seen perinecrotically, with induction of its target genes carbonic anhydrase 9 (CAIX), that plays a role in pH regulation and Glut-1, a transmembrane glucose transporter." (PMID 20565904, 2010). "Here we analyzed the relationships between hypoxia-related proteins (HIF-1α, Glut-1, leptin, ObR) and other cancer biomarkers in primary breast cancer and lymph node metastases." (PMID 20569445, 2010). "Our group and others have previously reported that HIF-1α protein overexpression is a marker of poor prognosis in primary breast cancer patients." (PMID 20624301, 2010). "Intratumoral hypoxia in breast cancer is marked by coordinated expression of such markers as HIF-1α, Glut-1, leptin and ObR." (PMID 20569445, 2010). "We also investigated the prognostic value of HIF-1α transcript expression levels in breast cancer and found a significant relationship between either clinicopathological characteristics or patient metastasis-free survival." (PMID 20624301, 2010). "Here we provide evidence that cellular iron deficiency contributes to HIF-1α stabilization, VEGF formation, and angiogenesis, all of which are important in carcinogenesis, metastasis, and breast cancer recurrence." (PMID 20723262, 2010). "When the HIF-1α protein level in the several breast cancer cell lines was cultured under ambient air, we found that variation in HIF-1α protein levels were inversely correlated with factor 26 expression (p = 0.0092) in a group of breast cancer cell lines." (PMID 20824128, 2010). "DCQ has previously been shown to decrease HIF-1α mRNA and protein expression levels in mouse mammary carcinoma cell lines." (PMID 21078189, 2010). "HIF-1α also activates miR-210; in human breast cancer cells, over-expression of hsa-miR-210 is induced by hypoxia, dependent on the function of HIF-1α and VHL (von Hippel-Lindau syndrome protein, involved in the ubiquitylation and degradation of HIF)." (PMID 19881911, 2009). "Knockdown of HIF-1α mRNA in MDA-MB-231 breast cancer cells decreased osteolytic lesion area and improved survival of mice in vivo." (PMID 19727403, 2009). "In preliminary experiments, we investigated the expression of VEGF, VEGFR2 HIF-1α and pFAK in breast cancer cell lines." (PMID 19919679, 2009).
breast cancer (continued). "In sporadic breast cancer, previous studies have shown that HIF-1α overexpression has a role in breast carcinogenesis and is correlated with a poor prognosis." (PMID 19724277, 2009). "In this study, we have shown frequent expression of HIF-1α in the neoplastic cells of BRCA1-related breast cancer and basal-like cancers (72 and 75%, respectively) of tumours being positive." (PMID 19724277, 2009). "Our findings suggest the value of further studies to investigate the mechanism of nuclear localization of FIH-1 and how it can be manipulated to target the HIF-1α pathway and other pathways in breast cancer therapy." (PMID 18096060, 2007). "In contrast to some adenocarcinomas (e.g. breast cancer), our results indicate that HIF-1α overexpression is related to good prognosis." (PMID 16035955, 2005). "Inflammatory signals (such as the role of IL-6 in burns and CKD), hypoxia and its core mediator HIF1α (in breast cancer, COVID-19, and burns), as well as specific metabolites (such as lactate in ccRCC and burns), collectively form a common ‘pathological stimulus pool’." (PMID 41498391, 2026). "However, additional clinical evidence is needed to ensure their targeting of HIF-1α in breast cancer." (PMID 41614951, 2026). "Evidence suggests that HIF1A may regulate TOR1B expression in basal-like breast cancer cells, linking TOR1B to hypoxia-related signaling pathways." (PMID 41596432, 2026). "Hypoxia (1% O2) exposure for 48 h also significantly enhanced the expression of β-catenin only in MCF-7 cells and BT-474 breast cancer cell lines, but increased HIF-1α expression and ALDH activity in all breast cancer cell lines tested, including the β-catenin-deficient MDA-MB-453 cells." (PMID 42224096, 2026). "We analyzed the expressions of the FA/HIF‐1α/CCL2 axis in breast cancer tissues from patients." (PMID 41160815, 2026). "Additionally, clinical trials testing the effect of sulforaphane on HIF-1α in breast cancer cells are still limited, highlighting the need for future research." (PMID 41614951, 2026). "PARK2 suppresses breast cancer metastasis by ubiquitinating and degrading HIF-1α." (PMID 39851497, 2025). "Although these mutations may change PRMT function, no experimental evidence currently connects them to angiogenesis-related pathways such as HIF-1α stabilization or VEGF/VEGFR signaling in breast cancer." (PMID 40791817, 2025). "However, to date, there is a paucity of data available examining the effect of WWOX/HIF1α signalling pathway on patient survival in breast cancer, hepatocellular, and glioblastoma." (PMID 41007296, 2025). "In this study, we discovered that STAMBPL1 could upregulate the expression of the hypoxia-inducible factor HIF1α in breast cancer cells." (PMID 40208233, 2025). "For example, high VEGF expression or elevated HIF-1α levels in breast cancer tissue may indicate a higher likelihood of response to anti-VEGF therapies or HIF inhibitors." (PMID 40851994, 2025). "Furthermore, immunohistochemistry analysis also shows that ZMYND8 and HIF1α expression are positively correlated in breast cancer." (PMID 40912652, 2025). "Besides HIF-2α, USP9X has been reported to inhibit degradation of the other key hypoxia factor, HIF-1α, in breast cancer." (PMID 40246814, 2025). "Moreover, HIF-1α activation promotes metabolic reprogramming, and breast cancer stem cell (BCSC) enrichment, which support chemoresistance." (PMID 39863855, 2025). "Further Western blot analysis showed that silencing ezrin reduced the expression levels of VEGF and HIF1α, while overexpression of ezrin increased these levels, indicating that ezrin may possess pro-angiogenic properties in breast cancer." (PMID 39827339, 2025). "MCU affects breast cancer progression and metastasis through altered ROS generation and HIF1α (hypoxia inducible factor 1 alpha) activity, and silencing MCU may increase caspase‐independent cell death in these models." (PMID 40985275, 2025).